HDAC6 (histone deacetylase 6)
Diseases named in the same sentence as HDAC6 in open-access papers (continued):
Sharing a sentence is not in itself a finding about the gene and the disease.
cancer (continued). "HDAC6 inhibition is a promising therapeutic approach for many diseases and is used to treat diseases such as neural degenerative disorders, ciliary and heart dysfunction, dementia, DM, lung injury, chronic kidney disease, spinal injury and cancer." (PMID 36749475, 2023). "Several studies had reported an in vivo anti-cancer activity of HDAC6 inhibitor." (PMID 36639650, 2023). "Indeed, the inhibition of HDAC6 is thought to beneficially contribute to the treatment of several types of cancer." (PMID 37373336, 2023). "Additionally, HDAC6 enhances key cancer immunotherapy targets, including PD-1 and its ligand PD-L1, crucial for immune checkpoint regulation." (PMID 37660065, 2023). "In addition to cancer cells, oxidative stress in stem cells and fertilized oocytes and the role of HDAC6 inhibition need further investigation." (PMID 36749475, 2023). "Altogether, these characteristics make HDAC6 a highly desirable target for cancer treatment." (PMID 38258065, 2023). "Among HDACs, HDAC6 has recently attracted interest owing to its functional role in cancers." (PMID 36639650, 2023). "It was reported that ARID1A suppressed histone deacetylase 6 (HDAC6) in OCCC directly, and HDAC6 nuclear expression was associated with immuno- and hypoxia tolerance and cancer stem cell phenotype in OCCC and upregulated following chemotherapy, leading to a poor prognosis." (PMID 36873929, 2023). "Furthermore, HDAC6 was found to associate with HIF-1α and with its transcriptional target, the VEGF receptor, thereby increasing their stability and activity in cancer cells." (PMID 38258065, 2023). "The design of specific inhibitors is the focus of a large number of medicinal chemistry programs in the academy and industry because lowering HDAC6 activity has been demonstrated to be beneficial for the treatment of several diseases, including cancer, and neurological and immunological disorders." (PMID 37626935, 2023). "Moreover, HDAC6-specific inhibitors (HDAC6i) have entered clinical investigation as part of a combination regimen for anti-cancer activity." (PMID 36810912, 2023). "Therefore, coupling the blocking of cancer epigenetic regulator (HDAC6) and ICI (VISTA) with Bexarotene and Oxymorphone is an unprecedented way to aggressively limit cancer pathogenicity that deserves experimental validation." (PMID 37660065, 2023). "In addition to cancer cells, HDAC6 inhibition induces oxidative stress injury in other types of cells." (PMID 36749475, 2023). "Thus, concomitant targeting of epigenetic modifiers LSD1 and HDAC6 using this LSD1/HDAC6 dual inhibitor represents a promising new strategy for the treatment of cancer that warrants further investigation." (PMID 36595522, 2023). "Besides, histone deacetylase 6 (HDAC6) has been demonstrated to be efficacious target for several cancers." (PMID 37660065, 2023). "Recent studies have shown that HDAC6 might be of dual function in the regulation of both AD and cancer." (PMID 36909942, 2023). "In addition, HDAC6 is a unique enzyme that participates in several cancer signaling pathways, including extracellular signal-regulated kinase (ERK) signaling." (PMID 36639650, 2023). "Since HDAC6 overexpression in ARID1A‐mutated cancers has been associated with several chemoresistant factors, we wondered whether inhibition of HDAC6 may be a promising therapy for those cancers." (PMID 35167193, 2022). "In addition, other studies have demonstrated that HDAC6 can regulate cancer-related signaling pathways, proving that HDAC6 has the potential to become a therapeutic target for cancer and has the capability to regulate immune cells." (PMID 35732647, 2022). "Notably, altered levels of both tubulin acetylation and HDAC6 were detected in several types of cancer." (PMID 36330589, 2022).
cancer (continued). "However, selective HDAC6 inhibitors alone were reported to be inadequate as anti-cancer compounds, and it was suggested that an anti-metastatic drug should be a non-selective HDACi or a selective HDAC6i in combination with other chemotherapeutics." (PMID 36559094, 2022). "Many reports showed that miRNAs targeting HDAC6 regulated cancer cell proliferation." (PMID 36076996, 2022). "Peptides that correspond to the binding domain of HDAC6 might regulate autophagy and overcome resistance to anti-cancer drugs." (PMID 36076996, 2022). "Previous research has found that HDAC6 may be a potential therapeutic target for cancer patients and has the ability to regulate immune cells." (PMID 35732647, 2022). "We consider that 7a may inhibit HDAC6 through this interaction mode, thereby playing its anti-tumor effect against Hela cancer cells." (PMID 35630812, 2022). "Recent studies showed that many cancer models are tolerant to HDAC6 inhibitor treatment." (PMID 36068335, 2022). "In cancer, HDAC6 is overexpressed and known to correlate with poor prognosis." (PMID 36402791, 2022). "Thus, the HDAC6 inhibitor can enhance the sensitivity of cancer cells to anti-cancer drugs by inhibiting autophagy." (PMID 36076996, 2022). "In addition, the NH2 washout in HeLa cells recovered the HDAC6 protein level within 3 h, confirming the suitability of use of NH2 as a reversible knockdown compound for HDAC6 protein in cancer cells." (PMID 35057104, 2022). "Inhibiting HDAC6 blocks the autophagy pathway in many cancer types." (PMID 35039480, 2022). "Overall, these results suggest that fine-tuning of the pro-invasive HDAC6-SARA-SMAD3 axis could be a better strategy towards effective cancer treatments." (PMID 35681731, 2022). "This review presents HDAC6 as a valuable target for developing anti-cancer drugs." (PMID 36076996, 2022). "As a result, the inhibition of HDAC6 activity represents an exciting therapeutic possibility in high‐grade/stage, invasive or metastatic EC harbouring ARID1A mutations, since metastasis is the main cause of death in patients with cancer." (PMID 35167193, 2022). "Our results suggest that inhibition of HDAC6 can be used to target excessive MYC in cancer." (PMID 36068335, 2022). "HDAC6 is thought to play a vital role in oncogene Ras-induced transformation, is a major factor in tumorigenesis and maintenance of the transformed phenotype, and is involved in cancer metastasis and migration." (PMID 36505774, 2022). "Our results indicate the involvement of HDAC6 in cancer may be more related to metabolic pathways than previously proposed." (PMID 35110592, 2022). "The upregulation of HDAC6 in a range of tumors suggests a pleiotropic role in cancer progression." (PMID 36355493, 2022). "In particular, several anti-cancer treatments targeting HDAC6 have been proposed." (PMID 36402791, 2022). "Downregulation of other cancer-promoting molecules such as HDAC6, required for efficient oncogenic tumorigenesis, and NCoA1, whose overexpression increases the number of circulating cancer cells and the metastasis, may overwhelm PTEN’s efficacy in this case." (PMID 35744941, 2022). "Exosomal molecules regulated by HDAC6 can serve as targets for developing anti-cancer drugs." (PMID 36076996, 2022). "The increased expression of HDAC6 was observed in anti-cancer drug-resistant cancer cells." (PMID 36076996, 2022). "The role of HDAC6 inhibitors in cancer therapy is still a matter of debate." (PMID 36068335, 2022). "Androgen receptor (AR) and histone deacetylase 6 (HDAC6) are important targets for cancer therapy." (PMID 33621955, 2021). "In addition to analyzing the relationship between HDAC6 and tumor immune infiltration, the present study also analyzed the correlation between HDAC6 and tumor microenvironment in pan-cancer." (PMID 34485153, 2021).
cancer (continued). "Accordingly, overexpression of HDAC6 might promote invasiveness of FLS; therefore, a HDAC6 inhibitor might prevent cancer cell-like tissue invasion and joint destruction by RA-FLS." (PMID 34225810, 2021). "In addition, we briefly summarized recent studies on the inhibitors of HDAC6 in these cancers, which suggests that this versatile enzyme is an attractive therapeutic target." (PMID 34938729, 2021). "Overexpression of HDAC1, HDAC2, HDAC3, and HDAC6 has been reported in different cancers." (PMID 35096000, 2021). "In the present study, we identified the potential value of HDAC6 in pan-cancer by primary analysis." (PMID 34485153, 2021). "Although autophagic function appears to be associated with particular tumor types, the involvement of HDAC6 in the autophagy pathway leaves no doubt as to its role as a possible target in cancer-specific models." (PMID 34944907, 2021). "However, when grouping benign and LG malignant SGT cases together, staining intensity for HDAC-2 and HDAC-6 successfully differentiated HG malignant from benign plus LG malignant tumors (p = 0.017 and p = 0.028, respectively)." (PMID 33799478, 2021). "Histone deacetylase 6 (HDAC6) is an established drug target for cancer treatment." (PMID 34583596, 2021). "In this study, we first analyzed the expression and prognosis of HDAC6 in pan-cancer." (PMID 34485153, 2021). "Currently, HDAC6 is regarded as a prognostic marker for several cancers 17-20." (PMID 33162791, 2020). "Moreover, we also observed a positive correlation between Smad7 and HDAC6 mRNA, and c-Jun and HDAC6 mRNA in several various cancer forms." (PMID 32888405, 2020). "Similarly, inhibition of the catalytic activity of HDAC6 promotes the dephosphorylation of AKT and ERK, associated with decreased cell proliferation and death of cancer cells." (PMID 32013157, 2020). "Because of the oncogenic role of HDAC6, it is conceivable that the deubiquitinating enzymes stabilizing HDAC6 could contribute to cancer." (PMID 32382008, 2020). "Furthermore, HDAC6-selective inhibitors have been designed to overcome the toxicity of pan-HDAC inhibitors in cancer clinical trials." (PMID 32961679, 2020). "A high level of HDAC6 has been found in multiple cancers, including pancreatic cancer and leukemia." (PMID 32961679, 2020). "Finally, we demonstrated that miR-206 prevents cancer progression in EC by downregulating HDAC6 via the PTEN/AKT/mTOR pathway." (PMID 32107418, 2020). "The role of the HDAC6 protein in cancer is also now well better understood." (PMID 32013157, 2020). "Additionally, HDAC6 deacetylates β‐catenin and thus represses its phosphorylation, leading to its nuclear translocation and promoting proliferation of cancer cells." (PMID 32985730, 2020). "Further analysis of the clinicopathological characteristics in paired HCC and adjacent nontumor tissues indicated that upregulation of microtubule acetylation or downregulation of HDAC6 was significantly correlated with malignant tumor progression and poor prognosis." (PMID 32206120, 2020). "HDAC6 binds to tubulin β3 and confers resistance to anti-cancer drugs in Malme3MR cells." (PMID 32626712, 2020). "Moreover, several HDAC6 targeting PROTACs also produced anti-proliferative effects in various cancer cells." (PMID 33322608, 2020). "HDAC6 localizes to both the cytoplasm and the nucleus of cancer cells." (PMID 30804456, 2019). "HDAC6 was observed to function as a promising therapeutic target for OCCC with ARID1A loss, in close association with immuno-modulation, response to hypoxia, and cancer stem cell phenotype." (PMID 30787326, 2019). "Moreover, several reports have shown that HDAC6 expression and function is altered in other non-cancer related conditions." (PMID 30992475, 2019). "HDAC6 also led to immuno- and hypoxia- tolerance and cancer stem cell phenotype." (PMID 30787326, 2019).
cancer (continued). "Though clinical trials of HDAC6 inhibitors to date have primarily focused on cancer therapies, there is growing evidence that HDAC6 inhibitors may have clinical applications in neuropsychiatric disorders as well." (PMID 30935091, 2019). "Furthermore, HDAC6 interacts with the cancer stem cell marker membrane glycoprotein CD133 and both were reported to stabilize β-catenin acetylation-dependently." (PMID 31561534, 2019). "Histone deacetylase 6 (HDAC6) is an attractive target for cancer therapeutic intervention." (PMID 31072216, 2019). "Therefore, inhibition of HDAC6 appears as a promising therapeutic strategy for reversing neurotoxic side effects of chemotherapy while improving the efficacy of cancer treatment." (PMID 30270813, 2018). "We recently found that efficient accumulation of a constitutively active FGFR3 mutant which is responsible for the lethal human disorder thanatophoric dysplasia type II (TDII) and is found in some bladder and other cancer types, was dependent on HDAC6 in cultured cells and in vivo." (PMID 29423038, 2018). "Various studies have indicated that combining a pan-HDAC or HDAC6 inhibitor with other anti-cancer drugs may increase efficacy." (PMID 29593536, 2018). "The growing interest for HDAC6-selective inhibitors is related to the modulation of acetylation of non-histone regulatory proteins (α-tubulin) implicated in cancer initiation and progression." (PMID 30096875, 2018). "Together, these suggest that selective HDAC6 inhibitors combined with other chemotherapy drugs may show promise and benefit for cancer treatment." (PMID 30176876, 2018). "Therefore, HDAC6 functions in cancer cells not only involve alterations in its expression but also activities that control its cellular deacetylation." (PMID 30176876, 2018). "Our findings and previous studies in which HDAC6 inhibitors were shown to act synergistically with chemotherapy drugs suggest that such combination therapies may be a rational strategy for the use of HDAC6 inhibitors in cancer treatment." (PMID 30594243, 2018). "Deacetylation of cortactin by SIRT1 and HDAC6 promotes cancer cell migration and invasion, which also could be observed in p300-null cells." (PMID 29416718, 2018). "Thus, HDAC6 currently attracts substantial attention as one of the potential drug targets for cancer treatment." (PMID 29391412, 2018). "Based upon the expression pattern of HDAC6 in different cancer cell lines, we presume its role in deacetylating ac-alpha tubulin in HeLa might be taken over by HDAC8 due to its significant overexpression compared to HDAC6." (PMID 29716651, 2018). "As HDAC6 inhibitors are at an early stage of clinical development, our findings may provide a novel therapeutic strategy and future applications for cancer therapy." (PMID 30594243, 2018). "The inhibitory effect of RanBPM on HDAC6 activity could therefore represent a major role for RanBPM in preventing cancer development, although the specific effects of RanBPM on HDAC6 cancer-promoting activities remain to be further explored." (PMID 28659384, 2017). "Importantly, we found that both MG132 and MLN4924 treatment stabilized HDAC6 at the endogenous level in multiple cancer cell lines including HT29, HCT116, and HeLa." (PMID 28599312, 2017). "As such, HDAC6-selective inhibitors have entered clinical trials for cancer therapy." (PMID 28599312, 2017). "To explore whether these cancer-derived SPOP mutants also affects their interaction with HDAC6, we performed GST pull-down assays and found that SPOP mutants including Y87C, F102C, W131G, F133L, or F133V, but not SPOP WT, failed to interact with HDAC6." (PMID 28599312, 2017). "Furthermore, depletion of SPOP using several independent shRNAs elevated the endogenous HDAC6 protein abundance in multiple cancer cell lines including HCT116, DU145, PC3, and HeLa." (PMID 28599312, 2017). "For these reasons, HDAC6 emerged as a valuable therapeutic target in cancer and other diseases." (PMID 28203307, 2017).
cancer (continued). "It is plausible that each E3 ubiquitin ligase is working in different cellular contexts, leading to their regulating HDAC6 in the context of cancer (SPOP) or Alzeimer's disease (CHIP) to impact different biological processes that warrants further in-depth investigation." (PMID 28599312, 2017). "Because HDAC6 has pro-migratory, pro-proliferative and anti-apoptotic functions in various cancer cell types, we investigated whether HDAC6 contributes to these functions in PAH-PASMCs." (PMID 28674407, 2017). "HDAC6 is emerging as an important therapeutic target for cancer." (PMID 27362804, 2016). "Thus, suppressing HDAC6 or MEK/ROCK together promotes normal epithelial organization in HER2-positive BT474 cancer cells that have low Cdc42 function." (PMID 26783207, 2016). "HDAC5 or HDAC6 knockdown dramatically inhibited tumor growth, especially HDAC6 knockdown, indicating that HDAC6 may have a more serious influence on cancer cell growth." (PMID 26747087, 2016). "HDAC6 inhibition has recently emerged as an attractive target for the treatment of cancer." (PMID 27362804, 2016). "The expression of HDAC6 in diverse tumours suggests an important role of HDAC6 in cancer." (PMID 25774669, 2015). "The downregulation of CD133 by an HDAC6 inhibitor inhibits cancer cell differentiation." (PMID 26556861, 2015). "Since failure to degrade misfolded proteins results in cell death, approaches that restore HDAC6 splicing may be key for therapeutic intervention in diseases such as cancer as well as for neurodegenerative diseases." (PMID 25782155, 2015). "Moreover, the assembly of SGs was unchanged in cells depleted of HDAC6 suggesting that SG-formation is largely uncoupled from HDAC6 function in cancer-derived cells." (PMID 25488811, 2015). "However, it is unclear how HDAC6 regulates the transcriptional activity and functional effect of NF-κB in cancer cells." (PMID 26388610, 2015). "Therefore, our findings point toward the existence of an endogenous, HDAC6- and protein deacetylation-dependent polysome assembly mechanism that can regulate oncogenic growth and potentially serve as a novel cancer therapeutic target." (PMID 24970821, 2014). "HDAC6 is a cancer drug target because of its role in transforming normal cells to cancer cells." (PMID 23644884, 2013). "Second, HDAC6 knockout MEFs are resistant to transformation; HDAC6 knockout mice might be less prone to cancer." (PMID 23644884, 2013). "The identification of HDAC6 as a key participant of hypoxia-induced cell invasion may have important therapeutic implications for the treatment of metastasis in cancer patients." (PMID 23405166, 2013). "Several lines of evidence suggest that HDAC6 is an ideal target for cancer therapy." (PMID 23644884, 2013). "Especially, HDAC6, a unique cytoplasmic member of class II, which mainly functions as α-tubulin deacetylase and Hsp90 deacetylase, has become a target for drug development to treat cancer due to its major contribution in oncogenic cell transformation." (PMID 22384180, 2012). "Until recently, HDAC6 involvement in response to DNA damaging anti-cancer agents began to emerge." (PMID 22957056, 2012). "Moreover, combining FDA‐approved HDAC6 inhibitors currently under clinical investigation with METTL3 inhibitors may offer a promising treatment strategy for cancers characterized by ciliary disorders, potentialy expanding therapeutic options." (PMID 39535388, 2025). "Moreover, genetic ablation of HDAC6 decreases GS in not only GBM but also in other cancer cells." (PMID 40162736, 2025). "Therefore, a detailed examination of these signalling events could enhance our understanding of HDAC6 inhibition in cancer." (PMID 39941046, 2025).